KCTD10 (potassium channel tetramerization domain containing 10)
Diseases named in the same sentence as KCTD10 in open-access papers (continued):
Sharing a sentence is not in itself a finding about the gene and the disease.
hepatocellular carcinoma (2 papers, 2021 to 2025). A malignant tumor that arises from hepatocytes. "On the other hand, it has to be noted that KCTD10 expression has been suggested as a favorable prognostic marker in patients affected by gastrointestinal stromal tumor, and in hepatocellular carcinoma (HCC) cells." (PMID 34001146, 2021).
adrenal gland tumors (1 paper, 2021). "Analysis of the COSMIC and GENT db confirm observations in melanoma, but also suggests KCTD10 overexpression in adrenal gland tumors, in a 6.3% of cancer tissues analyzed." (PMID 34001146, 2021). "Similarly, GENT2 db indicates a gene expression ratio of KCTD10 in adrenal tumor vs normal tissues [FC (fold change) = 1.41 (p value < 0.001)], suggesting the involvement of KCTD10 in this tumor type." (PMID 34001146, 2021).
alveolar soft part sarcoma (1 paper, 2013). An alveolar soft part sarcoma occurring in adults. "The expression of KCTD10 was observed in the primary tumors of osteosarcoma, rhabdomyo sarcoma, alveolar soft part sarcoma, and epithelioid sarcoma with various levels." (PMID 23977394, 2013).
brain tumor (1 paper, 2025). "When combined with anti-PD-1 therapy, KCTD10 overexpression significantly inhibited metastatic lung and brain tumor colonization and led to the strongly improvement in CD8a+ T cell infiltration." (PMID 40873559, 2025). "HE staining revealed that both Kctd10 overexpression and anti-PD-1 treatment independently reduced brain tumor burden, with the combined treatment exhibiting the most profound effect." (PMID 40873559, 2025).
breast tumor (1 paper, 2024). "In human breast tumor tissues, SLC7A11 levels were negatively or positively correlated with KCTD10 or USP18, respectively." (PMID 38959043, 2024). "Given breast tumor growth was significantly suppressed in an in vivo xenograft model following neddylation blockage and SLC7A11 inhibition, it promoted us to determine whether targeting KCTD10 or USP18 in combination with SLC7A11 inhibition could similarly affect tumor growth in this model." (PMID 38959043, 2024).
clear-cell ovarian carcinoma (1 paper, 2021). "Similarly, KCTD10 expression has been associated to unfavorable prognosis in patients with early-stage clear-cell ovarian carcinoma suggesting that in these contexts KCTD10 may be a therapeutic target." (PMID 34001146, 2021).
colon cancer (1 paper, 2024). "Indeed, in both breast and colon cancer cells, KCTD10 knockdown caused the accumulation of endogenous SLC7A11, whereas KCTD10 overexpression reduced the levels of endogenous SLC7A11 in a dose-dependent manner." (PMID 38959043, 2024).
congenital heart disease (1 paper, 2021). A heart disease that is present at birth. "The miR-592 may down-regulate KCTD10 expression during the development of congenital heart diseases." (PMID 34187934, 2021).
dyslipidemia (1 paper, 2016). "We systematically selected and genotyped 18 potentially functional polymorphisms in MVK, MMAB and KCTD10 by using the TaqMan OpenArray Genotyping System in a Chinese population including 399 dyslipidemia cases, 697 CHD cases and 465 controls." (PMID 27716295, 2016). "To determine whether polymorphisms in MVK, MMAB and KCTD10 are independently associated with the risk of dyslipidemia and CHD, we conducted a case–control study with 399 dyslipidemia cases and 465 controls in Han Chinese." (PMID 27716295, 2016). "Therefore, MVK, MMAB and KCTD10 genes may be candidates as susceptibility genes modulating HDL-C concentrations and then affect the risk of dyslipidemia and CHD." (PMID 27716295, 2016).
glioma (1 paper, 2025). A benign or malignant brain and spinal cord tumor that arises from glial cells (astrocytes, oligodendrocytes, ependymal cells). "Moreover, our finding of decreased expression of KCTD2 and KCTD10 aligns with reports in glioma, where reduced levels of these genes were associated with tumor progression." (PMID 40832836, 2025).
lung adenocarcinoma (1 paper, 2016). A carcinoma that arises from the lung and is characterized by the presence of malignant glandular epithelial cells. "In A549 lung adenocarcinoma cells, down-regulation of KCTD10 could inhibit cell proliferation." (PMID 27716295, 2016).
metastatic tumor (1 paper, 2022). "By carrying out quantitative real-time PCR (qRT-PCR), we found that, compared with those in the corresponding primary serous ovarian cancer, the mRNA levels of KCTD10, PCMT1, and ACTR10 were significantly increased in metastatic tumor tissues." (PMID 35033172, 2022).
non-small cell lung carcinoma (1 paper, 2025). A group of at least three distinct histological types of lung cancer, including non-small cell squamous cell carcinoma, adenocarcinoma, and large cell carcinoma. "In non-small cell lung cancer (NSCLC), KCTD10 expression is significantly downregulated in tumor tissues." (PMID 41164187, 2025).
ovarian carcinoma (1 paper, 2020). A malignant neoplasm originating from the surface ovarian epithelium. "The prognostic potential of the CCC-related biomarkers was validated in an external gene expression dataset (KM plotter) for OS of ovarian cancer patients (n = 655 for CCT5, KCTD10, and SETD3; n = 1,656 for the remaining CCC-related biomarkers)." (PMID 32133296, 2020).
tumor (9 papers, 2013 to 2025). "Immunofluorescence analysis showed that Kctd10 is co-localized with endothelial markers Cd31 and Cd34 in multiple subcutaneous tumors, suggesting that Kctd10 is associated with tumor angiogenesis." (PMID 40873559, 2025). "Immunofluorescence analysis revealed a decrease in normal blood vessels, as indicated by Cd31 labeling, whereas the number of tumor-associated blood vessels was markedly increased in Kctd10-knockout mice." (PMID 40873559, 2025). "The effect of endothelial-specific Kctd10 knockout on β-catenin expression likely reflect a non–cell-autonomous effect, in which the loss of Kctd10 in endothelial cells indirectly influences adjacent tumor and stromal cells through changes in the TME." (PMID 40873559, 2025). "The validation experiments conducted using the A2780 cell line further confirmed the tumor‐causing roles of KCTD2 and KCTD10 in OC." (PMID 40832836, 2025). "Given that endothelial cells in the tumor microenvironment are dispensable for tumor angiogenesis, we generated Kctd10flox/floxCDH5CreERT2/+ mice that specifically delete Kctd10 in vascular endothelial cells." (PMID 40873559, 2025). "Functional assays revealed that KCTD10 overexpression effectively suppressed tumor progression both in vitro and in vivo." (PMID 41164187, 2025). "Loss of Kctd10 in endothelial cells may disrupt this paracrine balance or compromise vascular integrity, thereby modulating β-catenin signaling in neighboring cells, suggesting the importance of endothelial–tumor cell crosstalk in mediating the systemic effects of endothelial gene perturbations." (PMID 40873559, 2025). "Functional assays in SKOV3 and A2780 cells demonstrated that overexpression of KCTD2 and KCTD10 significantly inhibited cell proliferation, migration, and colony formation, suggesting their tumor‐suppressive roles." (PMID 40832836, 2025). "Combination of KCTD10 activation or USP18 inactivation with SLC7A11 inhibition appears to be an effective approach to inhibit tumor growth." (PMID 38959043, 2024). "KCTD10 expression was significantly correlated with tumor size and postoperative metastasis (p <0.05, Fisher’s exact test)." (PMID 23977394, 2013). "Gene silencing of KCTD10 increased cell proliferation and invasion, suggesting that KCTD10 has a tumor-suppressive function." (PMID 23977394, 2013). "HE staining revealed decreased tumor cell density in Kctd10-overexpressing tumors." (PMID 40873559, 2025). "Therefore, overexpression of Kctd10, in conjunction with PD-1 blockade, effectively inhibits lung tumor metastasis and augments anti-tumor immunity." (PMID 40873559, 2025). "Additionally, CD31 expression, an angiogenesis marker, was downregulated in KCTD10-overexpressing subcutaneous tumors, indicating reduced tumor angiogenesis." (PMID 40873559, 2025). "Kctd10 exerts the function of tissue heterogeneity in regulating angiogenesis in both normal lung tissues and the tumor microenvironment, KCTD10 could promote tumor vascular normalization, making it a potential therapeutic target." (PMID 40873559, 2025). "The role of KCTD10 on Notch signaling may underlie its putative involvement not only in cardiac diseases but also in tumor types induced by Notch deregulation, among whom are hematopoietic tumors." (PMID 34001146, 2021). "We revealed that KCTD10 may exert tumor-suppressive effects in GIST." (PMID 23977394, 2013). "Kaplan-Meier Plotter survival analysis revealed that patients with high expression of KCTD10 exhibited significantly prolonger overall survival (OS) and post-progression survival (PPS), suggesting a potential tumor-suppressive role of KCTD10." (PMID 40873559, 2025). "As demonstrated in the GEPIA database analysis, elevated KCTD10 expression correlates with prolonged disease-free survival (DFS) in patients, suggesting its potential role in inhibiting tumor metastasis." (PMID 40873559, 2025).
tumor (continued). "Our study indicated the novel prognostic utility of KCTD10 in GIST, and suggested its tumor-suppressive effects on GIST cells." (PMID 23977394, 2013). "Given BRCA's significance in OC proliferation and therapeutic response, future research should investigate whether BRCA expression modulates the tumor‐suppressive effects of KCTD2 and KCTD10." (PMID 40832836, 2025). "KCTD10 was diffusely expressed in the membrane and cytoplasm of the tumor cells, while no KCTD10 expression was observed in sample S-7 from a patient who developed postoperative metastasis at 19 months." (PMID 23977394, 2013). "Additionally, we did not assess the potential correlation between KCTD2/KCTD10 and BRCA gene expression, which plays a crucial role in DNA repair and tumor progression in OC." (PMID 40832836, 2025).
cancer (5 papers, 2010 to 2026). A tumor composed of atypical neoplastic, often pleomorphic cells that invade other tissues. "High expression of KCTD10 is associated with a good prognosis of cancer." (PMID 38402311, 2024). "Although KCTD10 was shown to be involved in the growth of different cancer cell lines (52, –54), its role in regulation of cell death, particularly ferroptosis, is completely unknown." (PMID 38959043, 2024). "Of note, down regulation of KCTD10 can inhibit cell proliferation in carcinoma A549 cells." (PMID 20158880, 2010). "We next searched the Cancer Genome Atlas (TCGA) database for altered expression of SLC7A11, KCTD10, and USP18 in human cancer tissues." (PMID 38959043, 2024).
KCTD10 also shares sentences with these, for which no sentence is quoted: diabetes (2 papers); age-related macular degeneration (1); Burkitt lymphoma (1); cobalamin deficiency (1); colorectal adenocarcinoma (1); epithelioid sarcoma (1); heart disorder (1); lymphoblastic leukemia (1); Methylmalonic aciduria (1); neurotic disorder (1); osteosarcoma (1); rhabdomyo sarcoma (1); serous ovarian cancer (1).